FGF23 (fibroblast growth factor 23)
Diseases named in the same sentence as FGF23 in open-access papers (continued):
Sharing a sentence is not in itself a finding about the gene and the disease.
Sepsis (continued). "However, in community-dwelling adults, higher FGF23 concentrations were not independently associated with a higher risk of sepsis." (PMID 38313013, 2024). "Hence, the biological function of elevated FGF23 in sepsis remains unclear and warrants further studies." (PMID 33989306, 2021). "Therefore, whether blockage of FGF-23 is beneficial to sepsis patients requires further investigation." (PMID 31791247, 2019). "Collectively, the increased FGF-23 levels, decreased IGF-1 levels, and decreased 1,25(OH)2D levels in blood worsen systemic inflammation and multi-organ failures in sepsis patients." (PMID 31791247, 2019). "In hemorrhagic shock and sepsis-induced AKI rat model, Fgf23 gene expression is increased in bone marrow and is erythropoietin (EPO)-dependent." (PMID 30405444, 2018). "We hypothesized that a combined indicator that includes plasma FGF23, EPO, and Klotho would predict the development of AKI, mortality, and long-term CKD progression in sepsis patients." (PMID 37892163, 2023). "The combined FEK indicator, including Fibroblast Growth Factor 23, erythropoietin, and Klotho, predicted the development of AKI, short-/long-term mortality, and one-year CKD progression in critical care patients with sepsis." (PMID 37892163, 2023). "FGF23 signaling requires the presence of the co-receptor Klotho and there is convincing evidence that renal Klotho protein expression is reduced in septic patients with AKI, in septic foals, and in experimental sepsis models." (PMID 33989306, 2021). "Similar negative associations were observed for AXIN1 (OR = 0.715, CI = 0.517–0.990), FGF-23 (OR = 0.783, CI = 0.624–0.981), IL-4 (OR = 0.772, CI = 0.608–0.980), and OSM (OR = 0.755, CI = 0.592–0.962), whereas IL-2 showed a positive correlation with sepsis (OR = 1.320, CI = 1.008–1.729)." (PMID 39205680, 2024). "However, since FGF-23 and OSM were negatively associated with sepsis, they are unlikely to mediate the increased sepsis risk associated with Docosadienoate (22:2n6)." (PMID 39205680, 2024). "Two recent meta-analyses have found that FGF-23 can predict incident AKI in various patient populations in adults and children, combining data from critically ill patients, acute heart failure patients, patients with sepsis, and patients with acute respiratory distress syndrome." (PMID 38919625, 2024).
COVID-19 (20 papers, 2021 to 2025). A disease caused by infection with severe acute respiratory syndrome coronavirus 2. "While IL-6 production increases FGF23 and FGF23 functions to reduce vitamin D, it is unclear if low vitamin D levels in COVID-19 are associated with an inability to downregulate IL-6 and prevent a cytokine storm." (PMID 40687705, 2025). "The exact mechanisms underlying the association between FGF23, phosphocalcium metabolism and COVID-19 remain an active area of investigation." (PMID 37760804, 2023). "While these findings suggest a potential association between FGF23, phosphocalcium metabolism and COVID-19, it is important to note that the field of COVID-19 research is still evolving, and more studies are needed to establish definitive causal relationships." (PMID 37760804, 2023). "This study is one of the first clinical studies that evaluated the association between plasma FGF23 levels and COVID-19 in patients on renal replacement therapy." (PMID 36828412, 2023). "Discussion: Our results suggest that high plasma FGF23 levels are a risk factor for developing COVID-19 in ESRD patients." (PMID 36828412, 2023). "FGF23 has been shown to be involved in COVID-19-induced bone loss." (PMID 39941649, 2025). "Further research is required to determine whether FGF23 dysregulation plays a causal role in the severity of COVID-19 or if it serves as an indicator of disease progression." (PMID 37760804, 2023). "FGF23, a hormone primarily associated with regulating phosphate and vitamin D levels in the body, has gained attention as a potential biomarker in the context of COVID-19 due to its role in maintaining mineral homeostasis and its interactions with the immune system." (PMID 37760804, 2023). "Another review suggested that timely use of recombinant human erythropoietin (EPO), EPO analogs, acetylsalicylic acid, bioactive lipids, or FGF23 antagonists in genetically predisposed adults with the angiotensin-converting enzyme (ACE) D allele may induce detrimental effects in COVID-19 patients." (PMID 37637614, 2023). "FGF23 showed a very significant increase in COVID-19-positive patients at any time point, indicating a good diagnostic potential as confirmed by its ROC AUC." (PMID 39582872, 2024). "Certain studies have reported an inverse relationship between FGF23 and vitamin D levels in COVID-19 patients." (PMID 37760804, 2023). "This suggests a potential link between FGF23 dysregulation, disrupted phosphocalcium metabolism and the severity of COVID-19." (PMID 37760804, 2023). "Emerging research suggests a potential association between fibroblast growth factor 23 (FGF23), phosphocalcium metabolism and COVID-19." (PMID 37760804, 2023). "This is one of the first reports that evaluate the relationship between FGF23 and COVID-19 in this population." (PMID 36828412, 2023). "The aim of the present study was to examine the levels of FGF23 in COVID-19 patients and to find possible relations with other, commonly used biomarkers." (PMID 37637614, 2023). "Concerning additional baseline variables before the SARS-CoV-2 infection, the only parameter which differed between both groups was plasma FGF23 which was higher in those who developed COVID-19 (436 vs. 288 pg/mL, p = 0.026)." (PMID 36828412, 2023). "Data about the presence of COVID-19 symptoms and levels of multiple inflammatory markers, though limited, strongly suggest their role, FGF23 among them, in the control of COVID-19 clinical signs." (PMID 37637614, 2023). "Multivariate analysis showed that increased plasma FGF23 was independently associated with SARS-CoV-2 infection and severe COVID-19." (PMID 36828412, 2023). "A recent study determined that patients with asymptomatic SARS-CoV-2 infection had higher values of fibroblast growth factors (including FGF19, FGF21, and FGF23) compared to those with mild symptomatic COVID-19." (PMID 36828412, 2023).
COVID-19 (continued). "The immunoregulatory role of FGF23 has also been highlighted in COVID-19 and secondary immunodeficiency related to kidney disease." (PMID 37637614, 2023). "RANKL/OPG displays a good correlation with the bone fragility maker FGF23, indicating that this parameter is a reliable maker of bone fragility in COVID-19 patients and could provide useful and comprehensive information about inflammation-induced bone loss." (PMID 39582872, 2024). "Currently, no published data compares intact versus C-terminal FGF23 and its association with severe infections, including COVID-19." (PMID 36828412, 2023). "Understanding the intricate relationship between FGF23, phosphocalcium metabolism and COVID-19 could potentially open avenues for novel therapeutic interventions or prognostic indicators." (PMID 37760804, 2023). "In addition, people who had higher FGF23 titers had increased infection rates (23.7 vs. 13.2%, p = 0.034) and increased rates of severe COVID-19 (patients with COVID-related hospitalizations and deaths) (19.6 vs. 9.9%, p = 0.032)." (PMID 36828412, 2023). "Data about FGF23 levels and COVID-19 are scarce, yet interesting." (PMID 37637614, 2023). "Research has shown that FGF23 levels tend to be elevated in severe COVID-19 cases." (PMID 37760804, 2023). "It is speculated that the inflammatory response triggered by COVID-19 could impact FGF23 production and function, potentially leading to disturbances in phosphocalcium balance." (PMID 37760804, 2023). "Unfortunately, we were unable to obtain biochemical measures of inflammation (C-reactive protein and interleukin-6) and other markers (fibroblast growth factor 23 and prealbumin) in the majority of study participants at all time-points due to the COVID-19 pandemic." (PMID 35810296, 2022). "The anti-hypertensive and FGF-23 suppressive properties of calcimimetic drugs may contribute to their survival advantage in COVID-19 patients." (PMID 34444716, 2021). "Notably, COVID-19-infected patients with a history of CKD exhibited elevated levels of FGF23." (PMID 37626956, 2023). "CCL23, among the other seven proteins (IL-17C, MMP-10, FGF-19, FGF-21, FGF-23, and CXCL5), was higher in asymptomatic COVID-19 patients than in patients with symptoms." (PMID 37834869, 2023). "Thirdly, there was still a lack of information on several elements in the complex interplay linking serum phosphate level and mortality such as Corona Virus Disease 2019 (COVID-19) and phosphate-regulating hormones including parathyroid hormone (PTH) and fibroblast growth factor-23 (FGF-23)." (PMID 39026252, 2024). "In our patients, FGF23 displays a strong increase in COVID-19-positive patients compared to negative ones, with no significative variation over time, suggesting a good diagnostic potential, as confirmed by a very strong AUC ROC." (PMID 39582872, 2024). "Importantly, IL-17C, MMP-10, FGF-23 and CCL23 are upregulated only in asymptomatic participants early after infection, which strongly suggests their role in the control of COVID-19 clinical signs." (PMID 35479098, 2022). "Neither serum 25-OH-VD nor FGF-23 levels were obtained at the time of hospital admission, but our “baseline” values may offer a different perspective of the significance of VD deficiency, shortly before COVID-19 versus during active treatment when COVID-19 is ongoing." (PMID 34444716, 2021). "Non-severe COVID-19 was distinguished from other disease conditions in both children and adults by expression of PDGFA, AMFR, and FGF23, markers that have been observed to be upregulated in prior studies of acute COVID-19 infection." (PMID 37638019, 2023).
prostate carcinoma (20 papers, 2015 to 2025). A carcinoma that arises from epithelial cells of the prostate gland. "FGF23 gene expression has been found to be tightly associated with the development of prostate cancer, and FGF23 predicts a worse prognosis in prostate cancer." (PMID 36604721, 2023). "We identified multiple genes whose expression is altered by FGF23 that are associated with prostate cancer initiation and progression." (PMID 26019137, 2015). "Recently, three single nucleotide polymorphisms (SNPs) in the FGF23 gene were found to be associated with the development of prostate cancer." (PMID 26019137, 2015). "Three distinct SNPs in FGF23 are also associated with an increased risk of prostate cancer, indicating that FGF23 genetic variations increase prostate cancer susceptibility." (PMID 26483756, 2015). "FGF23 single-nucleotide polymorphisms (SNPs) are associated with increased risk of prostate cancer." (PMID 33520985, 2020). "As an example, in the context of prostate cancer, FGF23 serves as an autocrine growth factor, fostering proliferation, invasion, and the ability for cells to grow without attachment to a substrate in laboratory settings." (PMID 39267764, 2024). "Conversely, the suppression of FGF23 in prostate cancer cell lines results in a reduction in these phenotypes." (PMID 38397231, 2024). "In vitro studies showed that FGF23 promotes prostate cancer cell line proliferation, invasion, and anchorage-independent growth; however, FGF23 knockdown slows tumor growth in vivo." (PMID 37108717, 2023). "For this aim, FGF23 can act as an autocrine factor in prostate cancer cells stimulating tumor invasion and cell proliferation." (PMID 36926025, 2023). "Recent studies have found that FGF23 can promote the progression of prostate cancer, and in vitro studies have shown that it can promote the proliferation and migration of prostate cancer cells." (PMID 36604721, 2023). "FGF23 acts as an autocrine factor in prostate cancer cells stimulating tumor invasion and cell proliferation." (PMID 33520985, 2020). "S. Feng and colleagues demonstrated that prostate cancer, another tumor that thrives in the bone microenvironment, respond to Fgf23 by increased growth and MAPK signaling." (PMID 33057033, 2020). "FGF23 is overexpressed in prostate cancer tissues and studies in prostate cancer cell lines have shown that it acts as an autocrine, paracrine, and/or endocrine growth factor." (PMID 30736285, 2019). "Feng and colleagues showed that exogenous FGF23 promotes prostate cancer proliferation, invasion, and independent growth in vitro, whereas FGF23 knockdown in model systems decreased tumor progression both in vitro and in vivo." (PMID 31170159, 2019). "Exogenous FGF23 enhances proliferation, invasion and anchorage independent growth in vitro while FGF23 knockdown in prostate cancer cell lines decreases these phenotypes." (PMID 26019137, 2015). "In prostate cancer, FGF23 is present at increased levels in tumour tissues." (PMID 38397231, 2024). "FGF23 advances prostate cancer as an autocrine, paracrine, or endocrine growth factor." (PMID 37108717, 2023). "In tumor cells, namely prostate cancer, FGF23 similarly stimulates cell proliferation." (PMID 35011602, 2021). "In other malignancies affecting bone including prostate cancer or MM, an anti-FGF23 approach may also be useful as enhanced FGF23 or FGF23 signaling is typical of these tumor entities." (PMID 33520985, 2020). "For example, FGF23 may act as an autocrine, paracrine and/or endocrine growth factor in prostate cancer progression, but the relative importance of each factor depends on tumor expression level, tumor site, and underlying disease state." (PMID 32640686, 2020). "According to one study, the FGF23 plasma level is unchanged in prostate cancer, although prostate cancer cells may stimulate FGF23 expression in osteocytes." (PMID 33520985, 2020). "FGF23 is present at an increased level and promotes the progression of prostate cancer." (PMID 32879300, 2020).
prostate carcinoma (continued). "Thus FGF23 can potentially also act as an autocrine, paracrine and/or endocrine growth factor in prostate cancer that can promote prostate cancer progression." (PMID 26019137, 2015). "However, bone metastasis may account for the high FGF23 levels and symptoms of tumor-induced osteomalacia identified in prostate cancer patients." (PMID 36926025, 2023). "The investigations into the role of FGF23 in cancer have so far revealed two important aspects in general: In those forms of cancer affecting bone or originating from it such as MM or prostate cancer, FGF23 signaling may directly contribute to cancer biology/progression." (PMID 33520985, 2020). "FGF23 production may be subject to autocrine stimulation through FGFR in prostate cancer." (PMID 33520985, 2020). "However, none of these FGF23 gene SNPs are associated with regulatory features, although rs11063118 has been found to be associated with an increased risk of prostate cancer in a Korean population." (PMID 28212442, 2017). "Thus FGF23 is expressed in prostate cancer at increased levels." (PMID 26019137, 2015). "FGF23 expression was increased in patients with prostate cancer, as well as FGF23/FGFR1/αKlotho in various prostate cancer cell lines." (PMID 36926025, 2023). "The apparent adverse impact of elevated FGF23 on non-cardiovascular risk conceivably could reflect, at least in part, the ability of FGF23 to act as a growth factor for certain cancers, including possibly prostate cancer." (PMID 34359914, 2021). "FGF23 expression is enhanced in patients with castration-resistant prostate cancer, as well as FGF23/FGFR1/KL in different prostate cancer cell lines." (PMID 33520985, 2020). "Given that classical FGFs and FGF19 are also increased in prostate cancer, we analyzed expression microarrays hybridized with RNAs from of LNCaP cells stimulated with FGF2, FGF19 or FGF23." (PMID 26019137, 2015). "Bone metastasis may account for the high FGF23 levels and symptoms of TIO observed in patients with prostate cancer according to other studies." (PMID 33520985, 2020).
renal fibrosis (20 papers, 2017 to 2025). A final common manifestation of a wide variety of chronic kidney diseases characterized by glomerulosclerosis and tubulointerstitial fibrosis. "Does FGF-23 lead to myofibroblast activation and eventually cause renal fibrosis by damaging renal tubular epithelial cells?" (PMID 37016338, 2023). "In this study, we generated a murine model of CRS by inducing MI for 12 weeks, and we used this model to investigate the potential role of FGF23 in renal fibrosis as well as its underlying mechanisms." (PMID 33460402, 2021). "Downregulation or deficiency of Klotho, the co-receptor of FGF23, promotes oxidative stress and renal fibrosis." (PMID 33460402, 2021). "Therefore, we investigated whether an excess of FGF23 had an influence on renal fibrosis in mice with type 2 CRS, and we obtained evidence that the increase of circulating FGF23 caused by MI or overexpression of FGF23 can promote renal fibrosis." (PMID 33460402, 2021). "Indeed, FGF23/FGFR4 signaling is associated with muscle pathogenesis in the heart as well as renal fibrosis, processes that, if active in skeletal muscle, could explain the decline in muscle quality over time." (PMID 33876724, 2021). "In the AKI-CKD mouse model, serum FGF-23 levels were increased, and renal fibrosis occurred; moreover, the protein expression of β-catenin and p-Smad3 was upregulated." (PMID 37016338, 2023). "The increased expression of the FGF23 gene observed in the long-term MHV-1 infection mice suggests its direct or indirect contribution to renal fibrosis in chronically infected individuals." (PMID 37626956, 2023). "To further determine how FGF-23 promotes renal fibrosis, we treated IRI mice daily with the pan-FGFR inhibitor PD173074 for 2 weeks beginning on the first day after surgery." (PMID 37016338, 2023). "To explore the molecular mechanism by which the increase in FGF-23 promotes renal fibrosis, we used renal tubular HK2 cells to observe the changes in response to FGF-23 and FGFR inhibitors." (PMID 37016338, 2023). "LIPUS treatment effectively alleviated the decreases in the body weight and albumin/globulin ratio and the increases in the serum renal functional markers, fibroblast growth factor-23, renal pathological changes, and renal fibrosis in the CKD mice." (PMID 36362179, 2022). "In summary, our present findings indicate that excessive FGF23 can promote renal fibrosis in type 2 CRS mice by binding to FGFR4 and activating β-catenin signaling pathway." (PMID 33460402, 2021). "In this study, we observed that FGF23 promoted renal fibrosis in CRS mice with upregulation of TGF-β expression." (PMID 33460402, 2021). "We concluded that FGF23 promotes CRS-induced renal fibrosis mediated by partly activating FGFR4/β-catenin signaling pathway." (PMID 33460402, 2021). "Considering that FGF23 can bind with low affinity to FGFR1c, FGFR3c and FGFR4, we used a pan-FGFR inhibitor PD173074 to further test the effect of FGF23 on cardio-renal fibrosis." (PMID 33460402, 2021). "Using this model we have recently identified temporal and spatial increases in distal tubular FGF23 expression in early renal fibrosis, and demonstrated that FGF23 increases myofibroblast differentiation and fibrogenesis in a dose related fashion in vitro." (PMID 28848437, 2017). "FGF23 therefore joins a growing list of cytokines and growth factors that potentially regulate renal fibrosis." (PMID 28611350, 2017). "FGF23 is also expressed in damaged liver tissue, although it is only very weakly expressed in healthy liver and, on the same line, FGF23 has been shown to promote cardiac and renal fibrosis." (PMID 36830960, 2023). "On the same line, FGF23 has been shown to promote cardiac and renal fibrosis." (PMID 36830960, 2023). "The increase in FGF-23 may be associated with the progression of AKI to CKD and may mediate renal fibrosis via TGF-β and Wnt/β-catenin activation." (PMID 37016338, 2023).